SOD1 (superoxide dismutase 1)
Diseases named in the same sentence as SOD1 in open-access papers (continued):
Sharing a sentence is not in itself a finding about the gene and the disease.
amyotrophic lateral sclerosis (continued). "The aim of this case report is to increase the physician's awareness of the atypical phenotypes of amyotrophic lateral sclerosis and hopefully, to encourage further research on the factors responsible for delayed disease progression in patients with L144S SOD1 mutation." (PMID 37034065, 2023). "Although the orally available brain‐penetrant copper compound CuATSM has demonstrated promising effects in SOD1‐linked mouse models, the impact of CuATSM on disease pathology in patients with amyotrophic lateral sclerosis (ALS) remains unknown." (PMID 37317638, 2023). "Amyotrophic lateral sclerosis (ALS) is frequently caused by mutations in the SOD1 gene." (PMID 34616013, 2022). "Until recently, predictive testing for motor neuron disease (MND, also known as amyotrophic lateral sclerosis (ALS)) was available to only a small proportion of families who had a known disease causing genetic variant in a limited group of causal genes (e.g. SOD1)." (PMID 35379930, 2022). "(F) A form of hereditary Amyotrophic lateral sclerosis (ALS) is caused by SOD1 mutations." (PMID 36012138, 2022). "Some studies have found that motor neuron-specific ATG7 knockout mice carrying the pathogenic mutation of SOD1 may induce Amyotrophic Lateral Sclerosis." (PMID 34661876, 2022). "Also, activating mutation of SOD1 have been described to promote instead of inhibiting ferroptosis in Amyotrophic Lateral Sclerosis (ALS)." (PMID 35912247, 2022). "In addition, reactive oxygen species were shown to enhance proteasome activity in a Drosophila model of amyotrophic lateral sclerosis (i.e. mutant of the gene encoding superoxide dismutase 1)." (PMID 35025870, 2022). "Although the gain of function is causative for amyotrophic lateral sclerosis, SOD1 loss of function may play a role in ALS, contributing to the onset and progression of the disease." (PMID 35328090, 2022). "Superoxide dismutase (SOD1) gene variants may cause amyotrophic lateral sclerosis, some of which are associated with a distinct phenotype." (PMID 36371497, 2022). "Indeed, loss-of-function mutations in SOD1 with misfolding of the SOD1 protein are a well-known cause of the neurodegenerative disease amyotrophic lateral sclerosis (ALS)." (PMID 35538581, 2022). "Another interesting application of SOD–AuNP complexes is the development of highly sensitive colorimetric detection of the temporal evolution of SOD1 aggregates implicated in the pathology of amyotrophic lateral sclerosis (ALS)." (PMID 36358454, 2022). "We performed MD simulations for three allosteric systems, i.e., (i) the allosteric regulation of Pin1 induced by ligand binding, (ii) the conformational transition of SOD1 by G93A amyotrophic lateral sclerosis-linked mutation, and (iii) the activation of MEK1 by oncogenic mutations." (PMID 35351887, 2022). "Finally, we implemented PB-PE for efficient editing of an amyotrophic lateral sclerosis-associated mutation in the SOD1-gene of patient-derived hiPSC." (PMID 34773059, 2021). "Indeed, several mutations leading to SOD1 oligomerization and loss of function are associated with amyotrophic lateral sclerosis, which reinforces the importance of SOD1 upregulation during aging." (PMID 34303703, 2021). "Moreover, upon binding to DNA, SOD1 regulates the ROS-responsive expression of functional genes, including oncogenes and amyotrophic lateral sclerosis-linked genes." (PMID 33805942, 2021). "SOD1 is implicated in the pathogenesis of amyotrophic lateral sclerosis, a rare disease that primarily results in the degeneration of upper and lower motor neurons leading to muscle paralysis and atrophy, but which is also associated with other non-motor symptoms." (PMID 32012946, 2020). "However, some pathogenic Sod1 mutants that cause an inherited form of amyotrophic lateral sclerosis (fALS) seemingly counteract these processes." (PMID 32517371, 2020). "SOD1 is also associated with neurodegeneration in amyotrophic lateral sclerosis and AD34,35." (PMID 33633844, 2020).
amyotrophic lateral sclerosis (continued). "Indeed, a mutation in CCS that disturbs SOD1 metallation has been linked to familial forms of amyotrophic lateral sclerosis (ALS), which is characterized by similar SOD1 aggregate pathology as reported recently in PD." (PMID 30791479, 2019). "In humans, a mutant form of Sod1 is implicated in amyotrophic lateral sclerosis (ALS)." (PMID 30678160, 2019). "Mutations of the SOD1 gene are linked to some cases of Amyotrophic Lateral Sclerosis (ALS)." (PMID 30142602, 2018). "Misfolding of superoxide dismutase 1 (SOD1) is linked to amyotrophic lateral sclerosis." (PMID 29192167, 2017). "Mutation in SOD1 gene causes amyotrophic lateral sclerosis (ALS)." (PMID 28424594, 2017). "Mutations in SOD1 are known to be causative of amyotrophic lateral sclerosis." (PMID 27564311, 2016). "SOD1 was the first protein discovered in which mutations had an autosomal-dominant causal relationship to amyotrophic lateral sclerosis (ALS), an invariably fatal motor neuron degenerative disease characterized by progressive loss of motor neurons, with a lifetime risk by age 70 of about 1/1000." (PMID 27898663, 2016). "We analyzed whether the scope of the method can be extended to analyze aggregates in mouse and human tissue with amyotrophic lateral sclerosis (ALS) associated with superoxide dismutase 1 (SOD1) mutation." (PMID 25159221, 2014). "Furthermore, the reduction or induced mutation of SOD1 in astrocytes has been shown to induce neuronal degeneration and injury in ischemic and amyotrophic lateral sclerosis (ALS) murine models." (PMID 25136294, 2014). "Furthermore, amyotrophic lateral sclerosis (ALS) associated SOD1(G93A) mutant induces dissociation of Mat1 from a redox protein trx-1 and promotes Mst1 activation in spinal cord neurons in a reactive oxygen species-dependent manner." (PMID 23985272, 2013). "Indeed, abnormalities in a thiol-disulfide status of SOD1 have been proposed as a pathological change in a familial form of amyotrophic lateral sclerosis (fALS) that is caused by dominant mutations in SOD1." (PMID 24348334, 2013). "Amyotrophic lateral sclerosis is a chronic, fatal neurodegenerative disease, characterized pathologically by the death of motor neurons in the spinal cord and cortex, possibly induced by a deficiency in the enzyme superoxide dismutase 1 (SOD1; Rosen, 1993)." (PMID 23888142, 2013). "Intriguingly, a SOD1 Leu117Val missense mutation which yields a mutant protein indistinguishable from wild-type SOD1 (in terms of its activity, stability and folding) causes amyotrophic lateral sclerosis, but with unusually low penetrance and slow progression." (PMID 23820649, 2013). "Overexpression of mutant superoxide dismutase 1 (SOD1), which could result in amyotrophic lateral sclerosis, causes the upregulation of GRP78/BiP expression in COS7 cells and transgenic mice." (PMID 22605926, 2012). "In one of the first examples, DiGiorgio and colleagues have shown that motor neurons derived from hESC are sensitive to toxic effects of glial cells that carry a mutation in SOD1 gene, causing amyotrophic lateral sclerosis (ALS), a fatal neurodegenerative disease." (PMID 24089646, 2012). "Mutations in SOD1 cause a dominantly inherited form of amyotrophic lateral sclerosis (FALS)." (PMID 22768276, 2012). "SOD1 mutations are associated with amyotrophic lateral sclerosis (ALS)." (PMID 21976959, 2011). "Interestingly, in a transgenic mouse model of amyotrophic lateral sclerosis (ALS) expressing the G93A mutation of superoxide dismutase-1, a modulation of Necdin expression has been documented." (PMID 21912643, 2011). "Moreover, astrocytes bearing the amyotrophic lateral sclerosis (ALS) linked to superoxide dismutase 1 G93A (SOD1G93A) mutation also induce motoneuron killing in both coculture conditions and through soluble factors found in the culture media." (PMID 21698251, 2011). "Mutations in superoxide dismutase (SOD1) are causative for inherited amyotrophic lateral sclerosis." (PMID 21779368, 2011).
amyotrophic lateral sclerosis (continued). "The antisense oligonucleotide (ASO) tofersen (Qalsody; Biogen) is the first approved therapy for the treatment of amyotrophic lateral sclerosis (ALS) in adults who have a mutation in the SOD1 gene (SOD1-ALS)." (PMID 41233143, 2026). "We describe a 37-year-old man with coexisting amyotrophic lateral sclerosis (ALS) caused by a mutation in superoxide dismutase 1 (SOD1) and probable neurosarcoid myeloradiculitis." (PMID 42186501, 2026). "Although SOD1 is primarily recognized for its role in amyotrophic lateral sclerosis (ALS), a progressive motor neuron disease, pathogenic variants in this gene have also been associated with certain IPN forms, particularly CMT and HMN." (PMID 39932579, 2025). "This is perhaps exemplified in amyotrophic lateral sclerosis (ALS), where loss of superoxide dismutase 1 (SOD1) native activity (due to aggregate formation) leads to pathogenesis." (PMID 38041542, 2025). "Amyotrophic lateral sclerosis (ALS) is a fatal neurodegenerative disorder that results in the degeneration of motor neurons and is typically linked to toxic aggregates of mutant superoxide dismutase 1 (SOD1) protein." (PMID 40978462, 2025). "Recently, an ASO with RNase H1 mechanism has been approved for amyotrophic lateral sclerosis (ALS) patients with SOD1 mutations." (PMID 40268518, 2025). "T2 phosphorylation of T2D mutations increases the stability of the natural conformation of SOD1 and reduces the cytotoxicity of A4V-SOD1 (an amyotrophic lateral sclerosis (ALS)-associated mutation) in motor neuron-like cells." (PMID 40722913, 2025). "Amyotrophic lateral sclerosis (ALS) involves progressive degeneration of motor neurons, often associated with aggregated proteins such as superoxide dismutase 1 (SOD1) and TAR DNA-binding protein 43 (TDP-43)." (PMID 40940752, 2025). "The VALOR trial and its open label extension demonstrated the efficacy of the antisense oligonucleotide (ASO), tofersen, in familial amyotrophic lateral sclerosis (ALS) caused by variants in the SOD1 gene (SOD1‐ALS)." (PMID 40781905, 2025). "Recently the antisense oligonucleotide tofersen was approved as a disease‐modifying drug for the small subset of patients with amyotrophic lateral sclerosis (ALS) carrying a pathogenic superoxide dismutase 1 (SOD1) gene variant." (PMID 40491248, 2025). "In amyotrophic lateral sclerosis (ALS), for example, SOD1 found in circulating EVs has been proposed as a potential biomarker, offering diagnostic and prognostic value for ALS progression." (PMID 41462703, 2025). "Mutations in superoxide dismutase-1 (SOD1) are a common cause of amyotrophic lateral sclerosis (ALS)." (PMID 40450581, 2025). "Gene silencing therapy is an effective treatment for amyotrophic lateral sclerosis (ALS) patients carrying mutations in the superoxide dismutase‐1 (SOD1) gene aiming to reduce noxious forms of SOD1 in the central nervous system (CNS)." (PMID 40548824, 2025). "Human superoxide dismutase 1 (hSOD1) is an incredibly stable metalloenzyme and has become a paradigm for investigating the destabilizing effect on protein folding and misfolding linked to the fatal neurodegenerative disease, amyotrophic lateral sclerosis (ALS)." (PMID 40070688, 2025). "This process significantly contributes to the pathogenesis of several familial forms of amyotrophic lateral sclerosis (ALS) linked to mutations in the gene encoding the antioxidant enzyme Cu/Zn superoxide dismutase (SOD1)." (PMID 40223243, 2025). "Amyotrophic lateral sclerosis (ALS) is a progressive motor neuron disease for which important subtypes are caused by variation in superoxide dismutase 1 (SOD1)." (PMID 40957416, 2025). "Amyotrophic lateral sclerosis (ALS) is a progressive motor neuron disease for which important subtypes are caused by variation in the Superoxide Dismutase 1 gene SOD1." (PMID 40060668, 2025).
amyotrophic lateral sclerosis (continued). "Degenerative myelopathy has long been considered a natural animal model for Lou Gehrig’s disease, or genetic amyotrophic lateral sclerosis (ALS), due to the SOD1 mutation and its accumulation in motor neurons, similar to what is observed in humans." (PMID 40417363, 2025). "Background and Aims: Tofersen is approved for the treatment of amyotrophic lateral sclerosis (ALS) caused by SOD1 mutations." (PMID 40542572, 2025). "Most recently, Tofersen, employing the same chemical modifications as Mipomersen and Inotersen, was approved in April 2023 for amyotrophic lateral sclerosis (ALS) associated with SOD1 gene mutations." (PMID 40004514, 2025). "The variants in the superoxide dismutase 1 (SOD1) gene, primarily linked to amyotrophic lateral sclerosis (ALS), have also been associated with peripheral neuropathy." (PMID 39932579, 2025). "In the Asian population, SOD1 variants are the most common cause of amyotrophic lateral sclerosis (ALS)." (PMID 39351695, 2024). "Mutations in the human SOD1 gene increase its susceptibility to oxidation and are a cause of familial amyotrophic lateral sclerosis (ALS), an age-related neurodegenerative disease." (PMID 38414053, 2024). "Amyotrophic lateral sclerosis (ALS) is a neurodegenerative disease, and a mutation in the superoxide dismutase 1 (SOD1) gene is the cause of about 2% of adult cases of ALS." (PMID 38530400, 2024). "We have previously shown that the interaction of Derlin-1 with amyotrophic lateral sclerosis (ALS)-associated superoxide dismutase 1 (SOD1) mutants leads to pathological UPR and motor neuron dysfunction." (PMID 39080439, 2024). "Mutations in superoxide dismutase 1 (SOD1) that are associated with amyotrophic lateral sclerosis (ALS) cause its misfolding and aggregation." (PMID 37766226, 2023). "In mouse models carrying mutant variants of SOD1, such as G93A, several significant effects were observed in the context of amyotrophic lateral sclerosis (ALS)." (PMID 37834128, 2023). "For example, amyotrophic lateral sclerosis (ALS) is defined as the selective degeneration of upper and lower motor neurons caused by mutations of Cu/Zn superoxide dismutase 1 (SOD1) genes and dysregulation of mitochondrial complexes II and IV." (PMID 36978900, 2023). "Mutations in SOD1 protein have been implicated in various proteinopathies such as amyotrophic lateral sclerosis (ALS) and PD, due to its suggested role in regulating neuronal apoptosis." (PMID 38002320, 2023). "Amyotrophic lateral sclerosis (ALS) is an incurable motor neuron disease whose etiology remains unresolved; nonetheless, mutations of superoxide dismutase 1 (SOD1) have been associated with several variants of ALS." (PMID 36674509, 2023). "Numerous genes, including SOD1, mutated in familial and sporadic amyotrophic lateral sclerosis (f/sALS) share a role in DNA damage and repair, emphasizing genome disintegration in ALS." (PMID 37705092, 2023). "RBD has been reported in familial neurodegenerative conditions such as parkinsonism related to parkin and DJ-1 mutations, spinocerebellar ataxia type III, and amyotrophic lateral sclerosis (ALS) due to SOD1 mutations." (PMID 38275513, 2023). "Oxidative stress is implicated in many neurodegenerative diseases, such as Nrf2 destabilization in Parkinson’s Disease (PD) and SOD1 mutation in Amyotrophic Lateral Sclerosis (ALS)." (PMID 36675019, 2023). "Accumulation of misfolded superoxide dismutase‐1 (SOD1) is a pathological hallmark of SOD1‐related amyotrophic lateral sclerosis (ALS) and is observed in sporadic ALS where its role in pathogenesis is controversial." (PMID 37119480, 2023). "They found that SOD-1 loss and gain of function in C. elegans differentially contributed to the pathogenesis of Amyotrophic Lateral Sclerosis (ALS) in different neuronal populations." (PMID 35748965, 2022).
amyotrophic lateral sclerosis (continued). "Despite 3 decades of research, the basic mechanisms by which mutations in superoxide dismutase-1 (SOD1) trigger familial amyotrophic lateral sclerosis (ALS) remain a mystery." (PMID 36265587, 2022). "Mutations within Superoxide dismutase 1 (SOD1) cause amyotrophic lateral sclerosis (ALS), accounting for approximately 20% of familial cases." (PMID 35879519, 2022). "The tight binding of Cu and Zn ions to superoxide dismutase 1 (SOD1) maintains the protein stability, associated with amyotrophic lateral sclerosis (ALS)." (PMID 35630637, 2022). "Mutations in the human SOD1 gene are associated with familial amyotrophic lateral sclerosis (ALS), and result in substantially increased ROS concentrations in the nervous system." (PMID 35573837, 2022). "Amyotrophic lateral sclerosis (ALS) is caused by a number of mutations, with C9orf72 repeat expansions the most common genetic cause and SOD1 gain-of-function mutations the first genetic cause identified for this disease." (PMID 33823304, 2022). "Mutations in copper–zinc superoxide dismutase (CuZnSOD [SOD1]) are a cause of amyotrophic lateral sclerosis (ALS), and Sod1G93A mice develop ALS." (PMID 36500717, 2022). "Many mutations in human SOD1 are associated with amyotrophic lateral sclerosis (ALS), a nervous system disease that causes loss of muscle control." (PMID 35669513, 2022). "The problem is exemplified by the large number of reported SOD1 gene [MIM: 147450] variants implicated in amyotrophic lateral sclerosis (ALS [MIM: 105400])." (PMID 36522764, 2022). "After the discovery, in 1993 that mutations in the SOD1 gene are involved in familial forms of amyotrophic lateral sclerosis (ALS), research concerning the physiopathology of the protein strongly increased." (PMID 36009245, 2022). "Since SOD1 mutation correlates to neuron motor degeneration-related diseases such as amyotrophic lateral sclerosis (ALS), the SOD1-deficient mouse model now is recognized as a classic study model for ALS." (PMID 36299607, 2022). "Little is known about the early pathogenic events by which mutant superoxide dismutase 1 (SOD1) causes amyotrophic lateral sclerosis (ALS)." (PMID 35406813, 2022). "Degenerative myelopathy (DM) in dogs shares similarities with superoxide dismutase 1‐associated human amyotrophic lateral sclerosis (ALS)." (PMID 34410026, 2021). "Misfolding and toxic aggregation of numerous SOD1 mutants have been linked to the familial form of amyotrophic lateral sclerosis (ALS), and the role of SOD1 in the sporadic form of ALS is also debated." (PMID 34943155, 2021). "Mutations in Cu/Zn Superoxide Dismutase (SOD1) gene represent one of the most common causes of amyotrophic lateral sclerosis (ALS), a fatal neurodegenerative disorder that specifically affects motor neurons (MNs)." (PMID 34440152, 2021). "In this work, we investigate the β-barrel of superoxide dismutase 1 (SOD1) in a mutated form, the isoleucine 35 to alanine (I35A) mutant, commonly used as a model system to decipher the role of the full-length apoSOD1 protein in amyotrophic lateral sclerosis (ALS)." (PMID 34943155, 2021). "For example, in transgenic mice bearing mutation in SOD1 gene, which results in induction of amyotrophic lateral sclerosis (ALS), mRNA oxidation also occurred early, in the pre-symptomatic stage of the disease." (PMID 35173755, 2021). "ActiveDriverDB highlights three substitutions flanking the succinylated residue K123 of SOD1 that are annotated as likely pathogenic for amyotrophic lateral sclerosis, suggesting potential hypotheses of these substitutions and altered succinylation in this lethal neurogenerative disease." (PMID 33834021, 2021). "The aggregation of SOD1 is believed to be one of the chief causative factors behind the lethal motor neuron disease, amyotrophic lateral sclerosis (ALS)." (PMID 33825682, 2021).